NCOA3 (nuclear receptor coactivator 3)
Diseases named in the same sentence as NCOA3 in open-access papers (continued):
Sharing a sentence is not in itself a finding about the gene and the disease.
gastric cancer (13 papers, 2003 to 2025). A primary or metastatic malignant neoplasm involving the stomach. "UHMK1 also contributes to purine metabolism reprogramming by regulating the NCOA3/ATF4 axis and significantly promotes gastric cancer development." (PMID 35501324, 2022).
melanoma (10 papers, 2014 to 2025). A malignant, usually aggressive tumor composed of atypical, neoplastic melanocytes. "NCOA3, significant in melanoma susceptibility, is emerging as a therapeutic target due to its frequent amplification in cancers." (PMID 39338229, 2024). "Recently, scientists discovered that UV-induced DNA damage and melanoma susceptibility are regulated by the nuclear receptor coactivator NCOA3." (PMID 35936711, 2022). "Copy number alterations and point mutations in NCOA3 (AIB1) have been observed in human breast (31%) and CRCs (14%) and it is a transposon target in murine models of colorectal, liver, pancreas cancer, and melanoma." (PMID 29301589, 2018). "In melanoma cell lines and patient-derived xenografts, downregulation of NCOA3 expression, either through genetic silencing or small-molecule inhibition, markedly reduced melanoma proliferation." (PMID 35936711, 2022). "Its role in other cancers is unclear however it has been shown that overexpression of NCOA3 is a marker of melanoma outcome." (PMID 28650955, 2017). "Specifically, we applied a mRNA panel consisting of KI67 (indicative of cell proliferation), POLR2A, BRCA1, MTOR, NCOA2, and NCOA3 to highly scattering and autofluorescent human melanoma skin biopsy FFPE tissues obtained from and characterized by the UCI Dermatopathology Center." (PMID 35013281, 2022).
colon cancer (7 papers, 2018 to 2025). "MAD2L2 interacted with NCOA3 and suppressed proliferation and migration of colon cancer cells." (PMID 30613364, 2018).
liver cancer (6 papers, 2014 to 2025). An epithelial or non-epithelial malignant neoplasm that arises from the liver. "We also analyzed the correlation between NACO3, SP1 and TERT mRNA expression in liver cancer patients in the GEO database (GEO: GSE10143), the mRNA level of SP1 was a positive correlation with the NCOA3 (R2 = 0.7367, p < 0.0001) and TERT (R2 = 0.0.401, p < 0.0001)." (PMID 33239622, 2020). "Tumor tissues from liver-orthotopically xenografted mice fed a high protein diet or human liver cancer tissues showed TM4SF5-dependent macropinocytosis and NCOA3-correlated metastatic features, unlike mice fed a normal chow diet or human nontumor regions." (PMID 40186033, 2025).
Obesity (6 papers, 2012 to 2024). Accumulation of substantial excess body fat. "Emerging evidence from previous studies using animal models also suggests that the NCOA3 plays a critical role in lipid metabolism as well as adipogenesis and obesity." (PMID 32927662, 2020). "Emerging evidence from previous studies using animal models suggests that the NCOA3 gene (NCOA3) plays a critical role in lipid metabolism as well as adipogenesis and obesity." (PMID 26449542, 2015). "Previous studies provided evidence that the NCOA3 gene (NCOA3) plays a primary role in adipogenesis as well as obesity by regulating the gene expression of peroxisome proliferator-activated receptor γ (PPARγ) - the master regulator of adipocyte development and differentiation." (PMID 26449542, 2015).
pancreatic cancer (6 papers, 2018 to 2025). "The nuclear receptor coactivator-3 (NCOA3) is a critical modulator of musin expression that is critical in pancreatic cancer progression." (PMID 34683931, 2021).
leukemia (3 papers, 2018 to 2025). A malignant (clonal) hematologic disorder, involving hematopoietic stem cells and characterized by the presence of primitive or atypical myeloid or lymphoid cells in the bone marrow and the blood. "Regarding B cells, ATLL IgG strongly recognized proteins like SP110 and SP100, which are linked to B cell survival, NCOA3, associated with leukemia development, and BCAS4, related to cancer progression." (PMID 41303346, 2025).
osteoarthritis (3 papers, 2015 to 2023). A noninflammatory degenerative joint disease occurring chiefly in older persons, characterized by degeneration of the articular cartilage, hypertrophy of bone at the margins and changes in the synovial membrane. "NCOA3 has been previously associated, through GWAS studies, with osteoarthritis, bone mass, abnormal cartilage behaviour, and notch signalling pathway." (PMID 33326993, 2021).
Anxiety (2 papers, 2020 to 2021). Intense feelings of nervousness, tension, or panic often arise in response to interpersonal stresses. "NCOA3-/- mice show reduced amino acid levels in the brain, with increased anxiety behaviors in females, and higher pain threshold in both sexes." (PMID 32449767, 2020). "NCOA3-/- female mice show increased anxiety, whereas NCOA3-/- male mice show normal explorative behaviors." (PMID 32449767, 2020).
Hearing impairment (2 papers, 2021). A decreased magnitude of the sensory perception of sound. "Our work provides evidence of NCOA3 playing an important role in skeletal system homeostasis and suggests NCOA3 as a potential candidate gene associated with hearing impairment." (PMID 33326993, 2021). "By linkage analysis and exome sequencing we identified a rare missense variant in the gene NCOA3 (NM_181659:c.2810C > G:p.Ser937Cys) that segregated in the pedigree with hearing loss." (PMID 33326993, 2021). "Here, combining linkage analysis with exome sequencing and functional analysis we have reported for the first time an association between segregation of a rare variant in NCOA3 and hearing loss, suggesting a novel mechanism leading to the pathogenesis of hearing impairment." (PMID 33326993, 2021). "We identified a missense variant in NCOA3, c.2810C > G: p.Ser937Cys, of which computation predictions and frequency are compatible with the hypothesis of this variant being causative of hearing loss." (PMID 33326993, 2021). "NCOA3 (Nuclear Receptor Coactivator 3) comprises 23 exons, encoding a protein of 1420 amino acids, with a suggested function in the regulation of gene transcription, mediated by nuclear receptors and it has never been reported to be associated with hearing loss." (PMID 33326993, 2021).
invasive breast carcinoma (2 papers, 2013 to 2019). A carcinoma that infiltrates the breast parenchyma. "In addition, elevated expression of Ets1 and Ets2 identified in invasive breast cancers has been correlated with increased expression of the p160 nuclear receptor coactivators NCOA1 (SRC1) and NCOA3 (AIB/SRC3)." (PMID 23874775, 2013).
renal cell carcinoma (2 papers, 2021 to 2022). "Similarly, we confirmed the interaction between NCOA3 and PFKFB4 to modulate PPP flux in renal cell carcinoma." (PMID 34593007, 2021).
ulcerative colitis (2 papers, 2023 to 2025). An inflammatory bowel disease involving the mucosal surface of the large intestine and rectum. "Previous research has indicated that NCOA3 suppresses inflammation and mediates goblet cell differentiation in DSS‐induced ulcerative colitis." (PMID 40331881, 2025).
age-related hearing loss (1 paper, 2021). "Further functional studies to evaluate the precise effect of the missense variant p.Ser937Cys in NCOA3 function would add value in understanding age-related hearing loss in patients with autosomal dominant pathogenic variants in NCOA3." (PMID 33326993, 2021).
Alzheimer disease (1 paper, 2021). A progressive, neurodegenerative disease characterized by loss of function and death of nerve cells in several areas of the brain leading to loss of cognitive function such as memory and language. "Variants in other interaction partners of NCOA3 including insulin growth factor 1 (IGF1 rs5742643), HNF1 homeobox A (HNF1A rs1800574 and rs56348580), and IQ motif containing K (IQCK rs7185636) were associated with systolic blood pressure, type 2 diabetes, or Alzheimer’s disease, respectively." (PMID 34864818, 2021).
asthma (1 paper, 2021). "ADRB2 has previously been associated with asthma and NCOA3 is involved in transcriptional regulation and has previously been associated with BDR in Puerto Ricans with asthma." (PMID 33477890, 2021).
autosomal dominant non-syndromic hearing loss (1 paper, 2021). "Our findings (i.e., the identification of the second family reported globally with HL caused by a variant in NCOA3) further support the involvement of NCOA3 in the etiopathogenesis of ADNSHL, which should, thus, be considered as a new gene for autosomal dominant non-syndromic hearing loss." (PMID 34356059, 2021).
developmental delays (1 paper, 2022). "Chen's research showed that knocking out NCOA3 in mice caused developmental delays." (PMID 35898549, 2022).
diabetes (1 paper, 2024). "Podocyte‐specific NCOA3 knockout enhanced albuminuria, glomerular and podocyte injury induced by diabetes." (PMID 38483947, 2024). "In this study, we found that NCOA3 but not NCOA1 and NCOA2 decreased obviously in diabetic kidneys." (PMID 38483947, 2024).
Dyslipidemia (1 paper, 2015). "The association of NCOA3 polymorphisms and dyslipidemia was further investigated through inheritance models." (PMID 26449542, 2015). "In this study, we intended to analyze the association between polymorphisms of human NCOA3 and dyslipidemia." (PMID 26449542, 2015). "The present study aims to investigate the association between NCOA3 SNPs and dyslipidemia in the Chinese Han population." (PMID 26449542, 2015). "In this study, our findings indicated that variation in NCOA3 might influence the risk of dyslipidemia and serum lipid levels in Chinese Han population." (PMID 26449542, 2015). "In conclusion, our present study revealed that the polymorphisms in NCOA3 might be in association with dyslipidemia and serum lipid levels in the Chinese Han population." (PMID 26449542, 2015). "And it can be further concluded that the NCOA3 gene might have association with plasma lipid levels and dyslipidemia, especially with hypertriglyceridemia." (PMID 26449542, 2015). "In summary, this study demonstrated that variation in NCOA3 might influence the risk of dyslipidemia and serum lipid levels in Chinese Han population." (PMID 26449542, 2015). "There is scarcely any information about the relationship between NCOA3 SNPs and dyslipidemia in humans." (PMID 26449542, 2015).
Glomerular sclerosis (1 paper, 2024). Accumulation of scar tissue within the glomerulus. "Loss of NCOA3 induced spontaneous podocyte injury and glomerular sclerosis, indicating that NCOA3 deficiency was the driving force of podocyte damage." (PMID 38483947, 2024). "The results showed loss of NCOA3 aggravated podocyte injury, albuminuria, and glomerular sclerosis by decreasing podocyte autophagy in Fyn dependent way." (PMID 38483947, 2024). "Podocyte‐specific NCOA3 knockout aggravates albuminuria, glomerular sclerosis, podocyte injury, and autophagy in DKD mice." (PMID 38483947, 2024).
glomerulosclerosis (1 paper, 2024). A hardening of the kidney glomerulus caused by scarring of the blood vessels. "NCOA3 knockout aggravated podocyte injury, urinary albumin excretion, and glomerulosclerosis, and led to decreased autophagy in the DKD model." (PMID 38483947, 2024).
hypertriglyceridemia (1 paper, 2015). A laboratory test result indicating elevated triglyceride concentration in the blood. "Logistic regression analysis revealed that hypertriglyceridemia was associated with three NCOA3 SNPs (rs2425955, rs6066394, and rs6094753)." (PMID 26449542, 2015). "In the present study, our data showed that four NCOA3 SNPs were associated with plasma levels of triglyceride, and except rs10485436, three other SNPs of NCOA3 gene were associated with a decreased risk of hypertriglyceridemia." (PMID 26449542, 2015). "Except for SNP rs10485463, genotype distributions and allele frequencies of the other three NCOA3 SNPs (rs2425955, rs6066394, and rs6094753) were significantly different between hypertriglyceridemia subjects and normal group." (PMID 26449542, 2015). "We hypothesize that decrease in transcription and translation of NCOA3 caused by polymorphism rs2076546 may lead to decrease in PPARγ expression level which may lead to increase in the plasma levels of triglyceride and hypertriglyceridemia." (PMID 26449542, 2015). "The four NCOA3 SNPs were associated with plasma levels of triglyceride, and except rs10485436, three other SNPs of NCOA3 gene were associated with a decreased risk of hypertriglyceridemia." (PMID 26449542, 2015).
lentivirus infection (1 paper, 2020). Virus diseases caused by the Lentivirus genus. "To test whether NCOA3 bound to the TERT promoter to activate TERT transcription, we established HCC cell lines with stable knockdown or overexpression of NCOA3 by lentivirus infection." (PMID 33239622, 2020).
oral cancer (1 paper, 2021). "However, the role of NCOA3 in the regulation of oral cancer cell EMT has not been sufficiently elaborated." (PMID 33289330, 2021).
steatosis (1 paper, 2026). Increased lipid within the cytoplasm of cells. "Accordingly, a phosphorylation-deficient NCOA3 mutant drives CREB/CBP-mediated lipogenesis, whereas genetic or pharmacological NCOA3 inhibition prevents steatosis, hepatic inflammation, and profibrotic signaling." (PMID 41926189, 2026).
synovial sarcoma (1 paper, 2022). "Notably, synovial sarcomas express the fusion oncoprotein SYT-SSX1 which enhances symoylation of NCOA3 through interaction with the SUMO E3 ligase, PIASy." (PMID 35664317, 2022).
cancer (141 papers, 2006 to 2025). A tumor composed of atypical neoplastic, often pleomorphic cells that invade other tissues. "In particular, BeME-WithFun identified functionally coherent modules containing cancer associated genes, including previously unappreciated modules such as the NCOA3/NCOR2 module." (PMID 29023534, 2017). "Interestingly, module 7 contains two genes with co-occurring mutations: NCOR2 (nuclear co-repressor) and NCOA3 (coactivator), with the latter being a well-known cancer driver." (PMID 29023534, 2017). "NCOA3 (also known as amplified in breast cancer 1, AIB1) is a transcriptional coactivator that enhances the activity of nuclear hormone receptors through histone acetyltransferase activity." (PMID 40332052, 2025). "In fibroblasts cocultured with endothelial cells, we observed significant upregulation of genes associated with cancer progression (MALAT1, NEAT1), vascular endothelial growth factor (VEGFA), and proinflammatory cytokines (NCOA3, IRF1)." (PMID 39805002, 2025). "Mechanistically, NR5A2 and NCOA3 cooperate to upregulate NRF2, a transcription factor regulating antioxidant gene expression, and inhibiting NR5A2 or NCOA3 enhances BETi’s anti-cancer effects both in vitro and in vivo." (PMID 39867656, 2024). "Mechanistically, NR5A2 and NCOA3 act synergistically to increase Nrf2 expression and inhibit cancer cell ferroptosis." (PMID 39664391, 2024). "ANCO1 also acts as a transcriptional repressor that can bind to the p160 nuclear receptor coactivators, including amplified in breast cancer 1 (AIB1/SRC3/NCOA3)." (PMID 37511268, 2023). "In another study, the role of miR-137 was also investigated in a few cancer models, including UM, where it regulated cell viability in vitro by downregulating SRC3 (now renamed NCOA3, nuclear receptor coactivator 3)." (PMID 36765733, 2023). "Nuclear receptor coactivator 3 (NCOA3), also known as Steroid receptor coactivator 3 (SRC3) or Amplified in breast cancer 1 (AIB1), is a member of the p160 steroid receptor coactivator family." (PMID 35898549, 2022). "Reflecting these cancer-driver effects, NCOA3 has emerged as an attractive target for novel cancer therapeutics." (PMID 35626007, 2022). "Other mutated cancer genes included those involved in Wnt signaling (APC, AMER1), mitogen signaling (KRAS, BRAF), epigenetic modification (ARID1A, ARID2, DNMT3A, NCOA3) and DNA repair (RAD50, BRIP1, ERCC5, RECQL4)." (PMID 33776923, 2021). "In the CHRNB4-high subgroup, CHRNB4 was co-expressed with numerous genes, such as ADCY9, NOTCH3, ARNT, NCOA1, and NCOA3, which correlated with multiple cancer-related processes, but only one gene, FLT4, was co-expressed in the CHRNB4-low subgroup." (PMID 32455963, 2020). "Both in vitro and in vivo studies have demonstrated that NCOA3 is involved in many cancer processes through several mechanisms." (PMID 29545931, 2018). "Pharmacological hyperactivation of NCOA3 by MCB-613 has been shown to attenuate cancer cell growth in vitro and in vivo." (PMID 29545931, 2018). "NCOA3 mRNA levels were significantly upregulated in both taxol-sensitive and taxol-resistant cancer tissues relative to their adjacent normal tissues." (PMID 27831559, 2016). "The oncogenic role of NCOA3 has been well established in various animal models and human cancers such as breast, prostate, colorectal and endometrial cancers." (PMID 26287601, 2015). "The odds ratio of 22.2 indicates that the observed odds for molecules targeting “NCOA3” to be cancer cytotoxic is 22 times high than for the molecules which are known to target genes other than “NCOA3”." (PMID 24553133, 2014). "Changes in NCOA3 expression influence ERα-dependent gene expression and consequently modulate cellular processes that promote cancer such as proliferation, invasion and cell motility." (PMID 24304549, 2013).